EMC1 (ER membrane protein complex subunit 1)
Description:
Part of the endoplasmic reticulum membrane protein complex (EMC) that enables the energy-independent insertion into endoplasmic reticulum membranes of newly synthesized membrane proteins. Preferentially accommodates proteins with transmembrane domains that are weakly hydrophobic or contain destabilizing features such as charged and aromatic residues. Involved in the cotranslational insertion of multi-pass membrane proteins in which stop-transfer membrane-anchor sequences become ER membrane spanning helices. It is also required for the post-translational insertion of tail-anchored/TA proteins in endoplasmic reticulum membranes. By mediating the proper cotranslational insertion of N-terminal transmembrane domains in an N-exo topology, with translocated N-terminus in the lumen of the ER, controls the topology of multi-pass membrane proteins like the G protein-coupled receptors. By regulating the insertion of various proteins in membranes, it is indirectly involved in many cellular processes (Probable).
Synonyms: KIAA0090; CAVIPMR
Tractability: Small molecule: a structure with a bound ligand is known. Antibody: UniProt predicts a signal peptide or a membrane-spanning region. PROTAC: ubiquitination databases record sites on it; its protein half-life has been measured.
Gene: Protein-coding gene on chromosome 1 (19,215,660 to 19,251,552, reverse strand). Ensembl gene ENSG00000127463.
Subcellular location: Endoplasmic reticulum membrane
Gene Ontology:
Molecular function: membrane insertase activity; protein binding
Biological process: protein insertion into ER membrane by stop-transfer membrane-anchor sequence; tail-anchored membrane protein insertion into ER membrane
Cellular component: EMC complex; endoplasmic reticulum membrane; membrane; protein-containing complex; endoplasmic reticulum
Genetic constraint (gnomAD): Loss-of-function variants: 98 observed, 127.01 expected, observed/expected ratio (o/e) 0.77, 90% interval 0.65 to 0.91. The upper end of that interval is the gene's LOEUF score, 0.91, which puts it in group 3 of 6, group 1 being the genes least tolerant of losing a copy. Missense variants: 1,054 observed, 1,285.9 expected, observed/expected ratio (o/e) 0.82, 90% interval 0.78 to 0.86. Synonymous variants: 433 observed, 509.12 expected, observed/expected ratio (o/e) 0.85, 90% interval 0.79 to 0.92.
Gene-disease validity (ClinGen):
ClinGen rates the evidence that EMC1 causes each of these diseases.
complex neurodevelopmental disorder with motor features (autosomal dominant; autosomal recessive): Moderate. A complex neurodevelopmental disorder that involves more than one phenotype associated with the central nervous system, including but not limited to intellectual disability, autism, and seizures (epilepsy).
Homologues: Orthologues: chimpanzee EMC1 (99% identical), macaque EMC1 (99% identical), rabbit EMC1 (96% identical), guinea pig EMC1 (96% identical), mouse Emc1 (93% identical), dog EMC1 (93% identical), rat Emc1 (93% identical), pig EMC1 (91% identical), tropical clawed frog emc1 (70% identical), zebrafish emc1 (66% identical), Drosophila melanogaster EMC1 (28% identical), Caenorhabditis elegans emc-1 (20% identical).
Diseases named in the same sentence as EMC1 in open-access papers:
EMC1 is named in the same sentence as 23 diseases in open-access papers, as found by Europe PMC text mining. Sharing a sentence is not in itself a finding about the gene and the disease. The quoted sentences say what the papers report.
Cerebellar atrophy (7 papers, 2016 to 2024). Cerebellar atrophy is defined as a cerebellum with initially normal structures, in a posterior fossa with normal size, which displays enlarged fissures (interfolial spaces) in comparison to the foliae secondary to loss of tissue. "Mutations in EMC1 are associated with global developmental delay, hypotonia, scoliosis, visual impairment and cerebellar atrophy." (PMID 31263175, 2020). "Recently, loss–of‐function mutations in EMC1 were detected in three families with cerebral and cerebellar atrophy." (PMID 29271071, 2018). "Although the full function of the EMC complex is yet to be elucidated, it is interesting to note that mutations in EMC1 have recently been described in patients with a complex neurological syndrome that includes cerebellar atrophy." (PMID 27390132, 2016). "Intriguingly, the individuals who carry compound heterozygous variants in EMC1 seem to less frequently present with symptoms such as scoliosis, postnatal microcephaly, dysmophic features and cerebellar atrophy than the individuals who carry heterozygous or homozygous variants in EMC1." (PMID 37187958, 2023). "Finally, mutant EMC1 alleles were recently found to be strongly associated with various human neurodevelopmental disorders, including global developmental delay and cerebellar atrophy." (PMID 28012275, 2016). "Pathogenic homozygous variants in the EMC1 gene have been associated with a recessive neurodevelopmental disorder, characterized by pathognomonic GDD, cerebellar atrophy, ID, visual impairment, psychomotor retardation with epilepsy, and scoliosis." (PMID 32869858, 2020). "Homozygous variants of EMC1 are associated with GDD, scoliosis, and cerebellar atrophy, indicating the relevance of this pathway for neurogenetic disorders." (PMID 32869858, 2020). "Mutations in the EMC1 gene (MIM616846), an integral part of the ER membrane complex, have been recently implicated in individuals affected with cerebellar atrophy, visual impairment, and psychomotor retardation (MIM616875)." (PMID 29271071, 2018). "Mutations in EMC1 have been associated with GDD in several studies, where the affected individuals showed variable clinical presentation with major findings such as global developmental delay, cerebellar atrophy, psychomotor retardation, hypotonia, and visual impairment." (PMID 37187958, 2023).
developmental delay (5 papers, 2016 to 2023). "Our experimental evidence suggests that the EMC1 c.2376G>A variant is most likely to be loss-of-function, and that bi-allelic loss of function in EMC1 are the genetic cause for global developmental delay in the proband." (PMID 37187958, 2023). "In summary, we have identified novel compound heterozygous variants in EMC1 as the genetic cause in the individuals from a Chinese family affected with global developmental delay." (PMID 37187958, 2023). "Novel compound heterozygous variants in EMC1 have been identified in individuals with global developmental delay." (PMID 37187958, 2023). "In summary, we have identified a novel homozygous splice variant in EMC1 in a child with global developmental delay." (PMID 29271071, 2018). "Our findings are in line with the only other report of EMC1 mutations in individuals affected with developmental delay, hypotonia, scoliosis, and cerebral atrophy." (PMID 29271071, 2018). "In this study, we report a novel splice variant in the EMC1 gene in a proband born of a consanguineous marriage, who presented with early infantile onset epilepsy, muscle wasting, severe psychomotor retardation, and developmental delay." (PMID 29271071, 2018).
Cerebral atrophy (2 papers, 2018 to 2021). Atrophy (wasting, decrease in size of cells or tissue) affecting the cerebrum. "Individuals with EMC10 variants had higher rates of seizures compared to EMC1, and individuals with EMC1 variants had cerebellar or cerebral atrophy that was not seen in the EMC10 cohort." (PMID 33531666, 2021).
Azoospermia (1 paper, 2020). Absence of any measurable level of sperm,whereby spermatozoa cannot be observed even after centrifugation of the semen pellet. "Particularly, the cut-off of 2.3 μg/mL of the EMC1 was shown to distinguish normal spermatogenesis from obstructive azoospermia, with a 100% specificity, and obstructive azoospermia from NOA with a 100% sensitivity and a 73% specificity." (PMID 33022946, 2020).
cerebellar ataxia (1 paper, 2022). A neurological syndrome characterized by clumsy and uncoordinated movement of the limbs, trunk, and cranial muscles. "Akin to defective EMC1 presentation, we report signs of cerebellar ataxia with detectable loss of cerebellar volume, persistent hypotonia, movement disorders, CC thinning, and anomalies in the hippocampi in our cohort." (PMID 35684946, 2022).
congenital heart disease (1 paper, 2024). A heart disease that is present at birth. "In a three-generation exome sequencing study of congenital heart disease, mutations in Emc1 have been associated with cardiac disease, primarily aortic outflow tract abnormalities." (PMID 39456238, 2024).
endocrine cancers (1 paper, 2025). "Further analysis of additional ECM molecules, including VTN, EMC1, THBS3, and CLEC3B revealed a positive correlation trend with PEBP1/STK11 co-expression in endocrine cancers, while correlations in other cancer types varied, suggesting a context-dependent relationship." (PMID 40806276, 2025).
retinitis pigmentosa (1 paper, 2020). Retinitis pigmentosa (RP) is an inherited retinal dystrophy leading to progressive loss of the photoreceptors and retinal pigment epithelium and resulting in blindness usually after several decades. "The OMIM database lists a mutation of unknown significance linked to retinitis pigmentosa (hEMC1A144T) residing in the EMC1 distal propeller." (PMID 33236988, 2020).
sarcoidosis (1 paper, 2021). Sarcoidosis is a multisystemic disorder of unknown cause characterized by the formation of immune granulomas in involved organs. "SARS-CoV2 ORF8 host targets belonging to the sarcoidosis gene panel (IL17RA, EMC1, PLD3, GDF15, FKBP10, ADAM9, and PLAT) highlight significant pathways related to sarcoidosis pathogenesis." (PMID 34440765, 2021).
viral infection (1 paper, 2016). "Because EMC1 executes an important role during PyV infection, and that ER-to-cytosol membrane transport is essential during virus infection, we reasoned that the EMC1 is strategically localized at the ER membrane to control this entry step." (PMID 28012275, 2016). "Collectively, these results strongly suggest that EMC1 executes a specific function in promoting SV40 ER membrane penetration, consistent with its role in facilitating viral infection." (PMID 28012275, 2016).
neurodevelopmental disorder (4 papers, 2016 to 2024). A behavioral and cognitive disorder with onset during the developmental period that involves impaired or aberrant development of intellectual, motor, or social functions. "Variants in the subunit 1 of EMC (EMC1) have been implicated in neurodevelopmental disorders." (PMID 37187958, 2023).
infection (2 papers, 2016 to 2022). The state of being infected such as from the introduction of a foreign agent such as serum, vaccine, antigenic substance or organism. "The study confirmed that the ER membrane protein complex (EMC), as a member of EMC1, promotes viral transport in the ER and is associated with the body's infection mechanism." (PMID 36211821, 2022). "Moreover, EMC1 knockdown also markedly impaired infection by the human BK PyV (open bars)." (PMID 28012275, 2016). "We find that a member of the ER membrane protein complex (EMC) called EMC1 promotes SV40 ER membrane transport and infection." (PMID 28012275, 2016). "Thus EMC1 binds to SV40 at approximately the time point when the virus is expected to penetrate the ER membrane; this interaction is lost later in the course of infection, perhaps reflecting a completion of SV40 cytosol arrival." (PMID 28012275, 2016). "Specifically we find that EMC1, the largest component of a poorly-characterized ER transmembrane protein complex called ER membrane protein complex (EMC), is a C18 binding partner that promotes SV40 ER membrane penetration and infection; it also supports BK PyV infection." (PMID 28012275, 2016).
tumor (2 papers, 2022 to 2023). "HDLBP and EMC1 were upregulated in tumor tissue and correlated with poor survival." (PMID 36211821, 2022). "The HR < 1 downregulation of PTPN6 and IKZF3 is considered a tumor suppressor, while the HR > 1 upregulation of HDLBP and EMC1 is considered an oncogene." (PMID 36211821, 2022).
EMC1 also shares sentences with these, for which no sentence is quoted: cancer (3 papers); epilepsy (3); Retinal dystrophy (2); scoliosis (2); cardiac disease (1); Dengue (1); melanoma (1); microcephaly (1); movement disorder (1); myxoid chondrosarcoma (1).